SOX2-OT (SOX2 overlapping transcript)
Synonyms: DKFZp761J1324; NCRNA00043; SOX2OT
Gene: Long non-coding RNA gene on chromosome 3 (180,989,510 to 181,836,880, forward strand). Ensembl gene ENSG00000242808.
Diseases named in the same sentence as SOX2-OT in open-access papers:
SOX2-OT is named in the same sentence as 42 diseases in open-access papers, as found by Europe PMC text mining. Sharing a sentence is not in itself a finding about the gene and the disease. The quoted sentences say what the papers report.
breast carcinoma (15 papers, 2014 to 2024). "This study aimed to verify the biologic role of SOX2OT associated with SOX2 in tamoxifen-resistant breast cancer and to understand the potential relationship between TME and lnRNA SOX2OT." (PMID 38649821, 2024). "Moreover, SOX2OT has been identified as a novel biomarker linked to tamoxifen-resistant breast cancer, and its association with SOX2 has also been documented." (PMID 38649821, 2024). "The rs9839776 polymorphism in the SOX2OT gene is related to SOX2OT expression in breast cancer." (PMID 31827385, 2019). "While SOX2OT was highly expressed in luminal B type breast cancer, those in TAMR breast cancers were extremely suppressed." (PMID 38649821, 2024). "Conversely, higher SOX2OT levels correlate with a better prognosis in HR-positive breast cancer, as seen in the KM plot." (PMID 38649821, 2024). "The downregulation of SOX2OT in TAMR breast cancer indicates its involvement in resistance mechanisms." (PMID 38649821, 2024). "This study provides potential insights into the role of SOX2OT in tamoxifen-resistant breast cancer." (PMID 38649821, 2024). "Previous studies suggest that the diverse interactions between SOX2 and SOX2OT plays a crucial role in the progression of breast cancer." (PMID 38649821, 2024). "For example, LSINCT5 and Zfas one can promote the proliferation of breast cancer, HOTAIR suppresses invasion and migration of breast cancer, SOX2OT induces SOX2 expression in breast cancer, and SRA is the expression activator of breast cancer." (PMID 36744179, 2022). "Recent studies have found that lncRNA SOX2OT acts as a carcinogenic molecule in the pathogenesis of many human cancers, such as gastric cancer, colorectal cancer, and breast cancer." (PMID 31827385, 2019). "It is reported that SOX2OT is upregulated in various cancers including gastric cancer, breast cancer, lung cancer and so on." (PMID 29849506, 2018). "But overexpression of SOX2OT reduced cell proliferation of breast cancer, suggesting that the effect of SOX2OT on cell growth is controversial." (PMID 29849506, 2018). "Recent studies manifested that SOX2OT contribute to the tumor progression of lung cancer, esophageal cell cancer and breast cancer through its regulation cell cycle progression." (PMID 28489861, 2017). "In ER+ breast cancer cell lines, expression of SOX2OT is positively correlated with SOX2 expression level, albeit at lower levels." (PMID 26136768, 2015). "High expression levels of SOX2OT and SOX2 are associated with estrogen receptor status and tamoxifen sensitivity of breast cancer cells." (PMID 26136768, 2015). "A weak (r = 0.219) but highly significant (p = 2.23×10−13) correlation between expression of SOX2 and SOX2OT was found, emphasizing the potential importance of this signaling pathway in human breast cancer." (PMID 25006803, 2014). "In this report we show that SOX2OT positively regulates SOX2 expression, and the ectopic expression of SOX2OT in the breast cancer cell line MDA-MB-231 reduces the proliferation rate and increases anchorage independent growth." (PMID 25006803, 2014). "We therefore examined the expression of SOX2 and SOX2OT in a series of tamoxifen-resistant MCF-7 breast cancer sub-lines that had been cultured for prolonged periods either in the absence of estrogen or in the presence of the antiestrogen tamoxifen." (PMID 25006803, 2014). "To address this question, we compared SOX2 and SOX2OT expression in a large collection of breast cancer samples from TCGA." (PMID 25006803, 2014). "Currently, very little is known regarding SOX2OT expression in breast cancer and its role in tumor initiation or progression." (PMID 25006803, 2014). "Our findings highlight the potential role of SOX2OT in TAMR breast cancer progression." (PMID 38649821, 2024). "Therefore, SOX2OT expression was confirmed to be consistently downregulated in both TAMR cell lines as well as TAMR breast cancer tissues." (PMID 38649821, 2024).
breast carcinoma (continued). "In this study, we confirmed that SOX2OT is downregulated in tamoxifen-resistant breast cancer." (PMID 38649821, 2024). "Therefore, they proposed SOX2OT as an oncogene and demonstrated that SOX2OT-positive breast cancers had a more aggressive clinical course." (PMID 31319040, 2020). "Analysis of the genome-wide RNA transcript profiles from the Cancer Genome Atlas (breast invasive carcinoma gene expression) by RNA Seq data set in 1106 samples of breast cancer tissues revealed the concordant expression of SOX2OT and SOX2 in this somatic cancer." (PMID 26136768, 2015). "In conclusion, an earlier observation that the SOX2OT locus has complex architecture and is important during vertebrate development in a number of systems has been extended in this study to a series of human breast cancer lines." (PMID 25006803, 2014). "Interestingly, Sox2ot has been shown to positively regulate the expression of Sox2 in a breast cancer cell line, suggesting that it may be a regulator of Sox2 expression in repair Schwann cells too." (PMID 28903050, 2017). "Further studies should explore the intricate interactions between SOX2OT, SOX2, and TME in breast cancer subtypes." (PMID 38649821, 2024). "This suggests a more complex and multifaceted interaction between SOX2OT and SOX2 in tamoxifen-resistant breast cancer." (PMID 38649821, 2024). "SOX2OT was reported to upregulate SOX2 substantially and augment breast cancer cell growth, whereas knockdown of SOX2OT impeded SOX2 transcription in bladder cancer." (PMID 35415876, 2022). "Distinct differences in the expression patterns of SOX2OT and SOX2 were observed in breast cancer tissue samples." (PMID 26136768, 2015). "SOX2OT and SOX2 are highly expressed in estrogen receptor positive (ER+) breast cancer cell lines, in comparison with the ER– ones." (PMID 26136768, 2015). "We propose that SOX2OT plays a key role in the induction and/or maintenance of SOX2 expression in breast cancer." (PMID 25006803, 2014). "SOX2OT was consistently downregulated in TAMR cell lines and TAMR breast cancer tissue." (PMID 38649821, 2024). "The correlation of SOX2OT and SOX2 was also found in breast cancer tissues." (PMID 29849506, 2018). "In human cancers, SOX2OT is co-upregulated with SOX2 and OCT4 in esophageal squamous cell carcinoma and was also suggested to play key roles in the induction and/or maintenance of SOX2 expression in breast cancer." (PMID 27833660, 2016). "Recently, the disregulation of SOX2OT expression and its concomitant expression with SOX2 have become highlighted in some somatic cancers including esophageal squamous cell carcinoma, lung squamous cell carcinoma, and breast cancer." (PMID 26136768, 2015). "Moreover, SOX2OT and SOX2 are co-upregulated in suspension culture conditions of breast cancer cell lines which advocates the growth of cellular subpopulation with cancer stem cell-like properties." (PMID 26136768, 2015). "The induction of SOX2 by ectopic expression of SOX2OT establishes a possible signaling pathway but does not prove that this pathway is important in human breast cancer." (PMID 25006803, 2014).
esophageal squamous cell carcinoma (14 papers, 2014 to 2023). Esophageal squamous cell carcinoma (ESCC) is a type of esophageal carcinoma (EC) that can affect any part of the esophagus, but is usually located in the upper or middle third. "Recently, two novel splice variants of SOX2OT have been identified in esophageal squamous cell carcinoma and concordant expression of SOX2 and SOX2OT was observed." (PMID 25006803, 2014). "But the role of SOX2OT in esophageal squamous cell carcinoma (ESCC) and the association between SOX2OT and SOX2 remain unclear." (PMID 29849506, 2018). "SOX2OT has also been identified in esophageal squamous cell carcinoma and concordant regulated with SOX2." (PMID 28033431, 2016). "SOX2OT is a lncRNA that is mapped to the human chromosome 3q26.3 (Chr3q26.3) locus, and is highly expressed in colorectal cancer, lung cancer, breast cancer and esophageal squamous cell carcinoma." (PMID 29132362, 2017). "SOX2OT is also increased in hepatocellular carcinoma and lung cancer and acts as an oncogene, and SOX2OT may play an important role in promoting the development of esophageal squamous cell carcinoma and hepatocellular carcinoma." (PMID 29132362, 2017). "As we have previously reported, SOX2OT is spliced into several transcript variants, including SOX2OT, SOX2OT-S1, and SOX2OT-S2 which co-upregulated with master regulators of pluripotency, SOX2 and OCT4, in esophageal squamous cell carcinoma (ESCC)." (PMID 26136768, 2015). "Moreover, MTA3 downregulates SOX2OT, and the MTA3/SOX2-OT/SOX2 axis has been reported as a potential cancer stratification marker in human esophageal squamous cell carcinomas." (PMID 37519889, 2023). "The lncRNA MALAT1, which is overexpressed in esophageal squamous cell carcinoma (ESCC) and glioma, promotes tumor proliferation and metastasis capacity, and the lncRNA Sox2ot promotes hepatocellular carcinoma cell metastasis and is correlated with a poor prognosis." (PMID 27248828, 2016). "We have previ-ously reported a significant upregulation of the lncRNA SOX2OT and its intronic cod-ing gene, SOX2, in esophageal squamous cell carcinoma (ESCC) tissue samples." (PMID 26862518, 2016).
lung carcinoma (13 papers, 2015 to 2023). "indeed, in a computationally reconstructed portrayal of human transcription database resource (MiTranscriptome); SOX2OT expression is reported to be mostly associated with the two cancer types of glioblastoma and lung carcinoma." (PMID 30202240, 2018). "Accumulated GLI1 activated SOX2/SOX2OT transcription by interacting with their promoter, ensuring positive self-regulation and consistent activation of the GLI1-SOX2OT loop in lung cancer cells." (PMID 37149646, 2023). "Our data revealed that the GLI1/SOX2OT RNA loop is functionally mediated by m6A modifiers in lung cancer cells." (PMID 37149646, 2023). "We unveiled a novel GLI1/SOX2OT positive loop activated by METTL3/14/IGF2BP2-modified m6A methylation to reinforce the stemness of lung cancer cells." (PMID 37149646, 2023). "Correlation analysis indicated that the expression level of GLI1 is positively correlated to that of IGF2BP2, METTL3/14, and SOX2OT in lung cancer bulk tumor." (PMID 37149646, 2023). "Compared with paired adjacent normal tissues, lung cancer specimens exhibited consistently upregulated GLI1/SOX2OT/METTL3/14/IGF2BP2." (PMID 37149646, 2023). "RT-qPCR demonstrated that GLI1 or SOX2 overexpression remarkably stimulated the SMO/GLI1/SOX2OT/SOX2 axis in lung cancer cells." (PMID 37149646, 2023). "We performed data mining using the University of California Santa Cruz genome browser and Gene Expression Database of Normal and Tumor Tissues 2 (GENT2) and confirmed overexpression of SMO, GLI1, SOX2, and SOX2OT in lung cancer samples." (PMID 37149646, 2023). "In this study, expression level and phenotypic analyses (including proliferation and sphere formation assays) revealed that GLI1 and SOX2OT formed a positive loop to regulate the stemness of lung cancer." (PMID 37149646, 2023). "The overall survival curve of lung cancer patients generated by the Kaplan–Meier Plotter showed that high SOX2OT expression level is related to unfavorable prognosis." (PMID 37149646, 2023). "After cytoplasmic/nuclear RNA purification, SOX2OT is located mainly in the cytoplasm of A549 and H1299 lung cancer cells." (PMID 37149646, 2023). "GLI1 and the long non-coding RNA SOX2OT were positively regulated, and the GLI1-SOX2OT loop mediated the proliferation of parental and stem-like lung cancer cells." (PMID 37149646, 2023). "It's worth pointing out that high level of plasma exosomal SOX2OT was also found in pancreatic ductal adenocarcinoma 42, perhaps it reduces the specificity as a biomarker in the diagnosis of lung cancer." (PMID 32015683, 2020). "The Venn diagram represented that 90 genes are down regulated and 118 genes are up regulated upon SOX2OT inhibition in Lung cancer cell similar to glioblastoma cell." (PMID 30202240, 2018). "To date, only a few lncRNAs (including MALAT1, HOTAIR, H19, MEG3, GAS5, ANRIL, and SOX2OT etc.)have been reported to be dysregulated and functionally characterized in lung cancer and most of the studies were based on microarray expression data." (PMID 26862852, 2016). "We believe that SOX2OT acting as ceRNA to protect mRNA of METTL3/14/IGF2BP2 and guiding METTL3/14/IGF2BP2 to GLI1 mRNA is the pivotal mode of action of SOX2OT in GLI1 regulation since SOX2OT is located mainly in the cytoplasm of lung cancer cells (>85% in A549 and >70% in H1299 cells)." (PMID 37149646, 2023). "Additionally, in situ hybridization revealed that SOX2OT expression was higher in lung cancer specimens than that in adjacent normal tissues." (PMID 37149646, 2023). "Knockdown of SOX2OT in lung cancer inhibited cell proliferation by inducing G2/M arrest." (PMID 29132362, 2017). "Knockdown of Sox2OT expression suppressed cancer cell growth by inducing G2/M arrest, prohibiting S phase entry and inhibiting cell proliferation which correlated with reduced protein levels of Cdc2 and Cyclin B1 in human lung cancer cell lines." (PMID 28489861, 2017).
lung carcinoma (continued). "Recent studies have found that SOX2OT promotes GLI1 expression via histone H3 methylation and acetylation, leading to resistance to multiple therapeutic strategies in lung cancer." (PMID 37149646, 2023). "As SOX2 was positively modulated by its host gene SOX2OT in a cis-acting manner, we further investigated how SOX2OT interplays with GLI1 and functions in lung cancer stemness." (PMID 37149646, 2023). "SOX2OT has been demonstrated to promote GLI1 expression via histone H3 methylation and acetylation, leading to multiple drug resistance in lung cancer." (PMID 37149646, 2023). "For lung cancer, a panel consisting of SOX2OT, ANRIL, CEA, CYFRA21-1, and SCCA was reported for NSCLC diagnosis, while SOX2OT and ANRIL were described as biomarkers for NSCLC prognosis." (PMID 32675385, 2020). "Knockdown of SOX2OT in lung cancer decreased EZH2 expression and inhibited cell proliferation by inducing G2/M arrest, while knockdown of SOX2OT decreased SOX2 and OCT4 expression and inhibited stem cell pluripotency and tumourigenesis in oesophageal squamous cell carcinoma." (PMID 32019566, 2020).
glioma (10 papers, 2017 to 2024). A benign or malignant brain and spinal cord tumor that arises from glial cells (astrocytes, oligodendrocytes, ependymal cells). "Expression of SOX2OT in 118 surgical specimens from glioma patients who were receiving TMZ chemotherapy showed that SOX2OT level was positively associated with tumor grading (WHO I/II versus WHO III/IV) (p < 0.001), confirmed by qRT-PCR analysis." (PMID 32439916, 2020). "Expression of SOX2OT in various cell lines showed its expression level was higher in glioma cell lines than in normal human astrocytes (NHA)." (PMID 32439916, 2020). "Other reports have shown similar mechanisms, which suggested long noncoding RNA SOX2OT upregulated transcription factor SOX3 expression by down-regulating miR-194-5p or miR-122 in glioma cells." (PMID 30691465, 2019). "In this study, we demonstrated that SOX2OT was up-regulated in glioma tissues and cell lines, and SOX2OT expression increased as the pathological grade increased." (PMID 29132362, 2017). "SOX2OT expression was significantly increased in glioma tissues of different grades compared with normal brain tissues (NBTs), and the expression was positively correlated with the tumor grade." (PMID 29132362, 2017). "This study demonstrated that SOX2OT was highly expressed in glioma tissues, U87 and U251 cell lines and GSCs, and SOX2OT expression increased with increased pathological grade of the gliomas." (PMID 29132362, 2017). "ALKBH5 acts as a modification switch of lncRNA SOX2OT and participates in the lncRNA-mediated competitive endogenous RNA model to enhance the molecular stability and exploit the function of SOX2OT, thus affecting progression and drug resistance in glioma." (PMID 36675186, 2023). "To verify this hypothesis, we first detected the expression of SOX2OT in glioma tissues and cell lines and evaluated its clinical relevance." (PMID 32439916, 2020). "SOX3 and SOX2OT were highly expressed in glioma tissues and GSCs." (PMID 29132362, 2017). "Our results will suggest that SOX2OT might be a new molecular targets for the treatment of glioma." (PMID 29132362, 2017). "For example, SOX2OT is up-regulated in glioma tissue and glioblastoma stem cells, and knockdown of SOX2OT inhibits the proliferation, migration and invasion of cells, and the SOX2OT-miR-194-5p/miR-122-SOX3-TDGF-1 pathway forms a positive feedback loop for glioma cell stemness." (PMID 30482236, 2018).
glioblastoma (9 papers, 2016 to 2024). The most malignant astrocytic tumor (WHO grade IV). "SOX2OT is significantly upregulated in GSCs and glioblastoma tissues, and decreased expression levels of SOX2OT impede the malignant biological activities of GSCs by elevating miR-194-5p and miR-122 levels." (PMID 39015773, 2024). "For example, SOX2OT downregulates the expression of SOX3 by regulating miR-194-5p and miR-122, and SOX3 epigenetically activates SOX2OT expression by binding to the SOX2OT promoter and subsequently forming a positive feedback loop in glioblastoma stem cells." (PMID 32019566, 2020). "Then in this study, we aimed to explore the transcriptome changes in the SOX2OT knocked down glioblastoma and lung adenocarcinoma cell lines with the RNA sequencing to clear the cellular function of SOX2OT long non-coding RNA in cancer cells." (PMID 30202240, 2018). "For example, SOX2OT can downregulate the expression of SOX3 by regulating miR-194-5p and miR-122, so as to regulate JAK/STAT pathway, inhibit the transcriptional expression of TDGF-1, and affect the biological behavior of glioblastoma stem cells." (PMID 34552054, 2021). "In glioblastoma cells, the transcription factor SOX3 induces Cripto expression and promotes proliferation, invasion and migration, possibly via the long non-coding RNA SOX2OT, which targets miR-194-5p and miR-122 and results in Cripto expression." (PMID 32517087, 2020).